USP16 (ubiquitin specific peptidase 16)
Diseases named in the same sentence as USP16 in open-access papers (continued):
Sharing a sentence is not in itself a finding about the gene and the disease.
cancer (10 papers, 2011 to 2025). A tumor composed of atypical neoplastic, often pleomorphic cells that invade other tissues. "A study of those rare cancers which have inactivating USP16 mutations would reveal whether the compensatory mechanisms proposed here are also operating in vivo." (PMID 34136489, 2021). "This review summarizes recent advances in USP16 studies, highlighting its potential role in cancer and immune response." (PMID 36980227, 2023). "USP16 has been considered a target for cancer chemotherapy, but our results suggest that treatment would select for escape mutants that are resistant to USP16 inhibitors." (PMID 34136489, 2021). "There are some examples of apparent down-regulation of USP16 in cancer but USP16 mutation is rare in primary cancers (data from TCGA Project17) which may be consistent with its important role in the cell cycle and DNA repair, and a reason why it has been considered as a cancer drug target." (PMID 34136489, 2021). "The third feature was the protein-coding gene USP16, reported to regulate tumor development by modulating the proliferation and death of cancer cells." (PMID 33918195, 2021). "On that basis one might consider USP16 as a target for cancer chemotherapy and indeed that has been proposed." (PMID 34136489, 2021). "Similarly, we revealed that TERC promotes cellular inflammatory response by upregulating the expression of immune-related genes such as LIN37, TPRG1L, TYROBP and USP16 in human normal and cancer cells." (PMID 31294790, 2019). "Here, I will focus on the emerging roles of the H2A DUBs USP3, USP16, USP44, BAP1, and MYSM1 in HSC maintenance and cancer." (PMID 26442100, 2015). "In the present study, we found that the targeted disruption of USP16, but not other deubiquitinases of c-Myc, reduced c-Myc protein levels in PCa, indicating that DUBs have different functions in different cancers." (PMID 33546726, 2021).
tumor (8 papers, 2016 to 2025). "Correlation analysis of the expression of USP16 and clinicopathological parameters showed that low levels of USP16 were associated with high tumour stages and poor differentiation." (PMID 27633997, 2016). "Collectively, USP16 may serve as a diagnostic marker and treatment target for c-Myc-driven tumor growth." (PMID 36980227, 2023). "Finally, we assessed the expression status of USP16 in 100 HCC patients by immunohistochemistry staining to evaluate the association of USP16 with malignant tumour phenotypes." (PMID 27633997, 2016). "USP16 inhibits reactive oxygen species (ROS)-induced p38 activation that would otherwise be tumor suppressive." (PMID 36980227, 2023). "Down-regulation of USP16 in the liver tumor cell line promotes its colony formation and tumor growth, leading to stem-like features." (PMID 36980227, 2023). "USP16 was found to be frequently downregulated in human HCCs and correlates with advanced tumor stages and disease progression." (PMID 36980227, 2023). "Immunohistochemistry staining was performed to detect the expression of USP16, Ki67, and c-Myc in xenograft tissues and clinical tumour tissues." (PMID 33546726, 2021). "Intriguingly, in accordance with the tumour suppressive functions of USP16, USP16 depletion was capable of inhibiting P21 expression but increasing Bcl-XL and Bcl-2 expression in Huh7 and PLC/PRF/5 cells." (PMID 27633997, 2016). "In this study, we have revealed a tumour suppressive function of USP16 in liver tumour cells and demonstrated that USP16 downregulation is a key event that is critical for Ct-HBX-mediated pro-tumorigenic activity." (PMID 27633997, 2016). "IHC staining demonstrated that xenograft tumours with USP16 inhibition exhibited increased Ki67 expression in comparison with control tumours." (PMID 27633997, 2016). "In human HCCs, USP16 was frequently downregulated, and the decreased expression of USP16 was correlated with high tumour stages and poor differentiation status." (PMID 27633997, 2016). "Liver tumour cells with forced down-regulation of USP16 exhibited increased capabilities for colony formation and tumour growth in vivo." (PMID 27633997, 2016). "We show that USP16 has the capacity to inhibit tumour formation and tumour cell stemness properties." (PMID 27633997, 2016). "The results showed that the tumours derived from Huh7–sh-Usp16 cells grew more vigorously, as evidenced by the tumour volumes and weights, than those formed by control cells." (PMID 27633997, 2016). "Conversely, ectopic expression of USP16 suppresses the tumor-promoting activity of Ct-HBx102." (PMID 40607251, 2025). "Interestingly, USP16 was expressed in both the nucleus and cytoplasm and was markedly decreased in tumour tissues." (PMID 27633997, 2016). "Moreover, in silico analysis of the HCC GSE14323 dataset, which includes a relatively large number of HCC samples, confirmed the downregulation of USP16 expression in tumour samples." (PMID 27633997, 2016). "The results of in vivo tumour formation further showed that knockdown of USP16 could significantly enhance the tumorigenicity of tumour cells." (PMID 27633997, 2016). "In addition, we found that the protein levels of USP16 were decreased in 6 of 10 cases in paired tumour and non-tumour HCC tissues." (PMID 27633997, 2016). "In addition, USP16 inhibition promoted stem-like properties in tumour cells, as evidenced by their spheroid formation and chemo-responsiveness." (PMID 27633997, 2016). "Furthermore, ectopic expression of USP16 in tumour cells significantly abrogated the tumour promoting activities of the Ct-HBx proteins (HBxΔ35), leading to decreased tumour cell viability and tumour growth." (PMID 27633997, 2016). "In addition, the inhibition of USP16 led to a delayed tumour onset in nude mice." (PMID 33546726, 2021).
tumor (continued). "The deubiquitination of histone H2A on lysine 119 by 2A-DUB/MYSM1, BAP1, USP16, and other enzymes is required for key cellular processes, including transcriptional activation, apoptosis, and cell cycle control, during normal hematopoiesis and tissue development, and in tumor cells." (PMID 32466590, 2020). "We further examined whether USP16 exerted suppressive activities on tumours grown in vivo." (PMID 27633997, 2016). "We further corroborated the suppressive effects of USP16 on the oncogenic activities of Ct-HBx in vivo by injecting HBxΔ35-transduced Huh7 cells and HBxΔ35, USP16-cotranduced Huh7 cells into nude mice and measuring the sizes and weights of the xenograft tumours after 3 weeks." (PMID 27633997, 2016). "The expression of USP16 is significantly suppressed by Ct-HBX, thereby inhibiting tumor proliferation." (PMID 40607251, 2025). "Clinically, the downregulation of USP16 occurs frequently in HCC tissues and correlates with clinical stages and tumour cell differentiation." (PMID 27633997, 2016). "To test this, we crossed Tg-SwDI mice with Usp16+/- mice to generate Tg-SwDI/Usp16+/- mice, which do not show tumor formation." (PMID 35311644, 2022). "Disruption of the intricate balance of ubiquitin marks due to the loss-of-function of a DUB has been shown to severely impact DSB repair, and may promote cancer formation, as indicated by tumor suppressor functions of BAP1, USP16, and other DUBs." (PMID 32466590, 2020). "In addition, USP16 knockdown decreased the responses of tumour cells to chemo-drugs, as evidenced by alterations in the IC50 values of the tumour cells after exposure to 5-fluorouracil (5-FU) and adriamycin." (PMID 27633997, 2016). "Consistently, clinical data present in the study also demonstrate decreased levels of USP16 in HCC tumours compared with non-tumour tissues." (PMID 27633997, 2016). "In contrast to the COOH-terminal truncated forms, Overexpression of full-length HBx (FL-HBx) did not reduce but slightly increase USP16 expression in HepG2, PLC/PRF/5 tumour cells and liver LO2 cells." (PMID 27633997, 2016). "We further examined the expression levels of USP16 in the paired HCC tissues and found that the mRNA levels of USP16 were significantly decreased in tumour tissues compared with those in the adjacent non-tumour specimens." (PMID 27633997, 2016).
degenerative diseases (1 paper, 2018). "All together, these findings link important stem cell regulators like Bmi1/Usp16 and Cdkn2a to Wnt signaling, and have implications for designing therapies for conditions, like DS, aging or degenerative diseases, where the Wnt pathway is hampered." (PMID 30504774, 2018).
liver (1 paper, 2023). "The level of USP16, a deubiquitinase widely implicated to function in cell proliferation, division, and differentiation, was dramatically increased upon liver IRI." (PMID 37777507, 2023).
USP16 also shares sentences with these, for which no sentence is quoted: Alzheimer’s dementia (2 papers); Alzheimer's disease (1); autoimmune encephalitis (1); behavioral disorders (1); cognitive deficits (1); female subfertility (1); immune disease (1); lung carcinoma (1); type II diabetes (1).